HFE (homeostatic iron regulator)
Diseases named in the same sentence as HFE in open-access papers (continued):
Sharing a sentence is not in itself a finding about the gene and the disease.
iron overload (continued). "The H63D mutation of the HFE gene also underlies HH but is associated with iron overload-linked organ disease only in 30% of cases and usually in the presence of comorbidities, alcoholism, or drug abuse." (PMID 24368960, 2013). "The HFE gene H63D mutation underlies Hereditary Haemochromatosis (HH), which needs treatment to prevent organ damages by iron overload." (PMID 24368960, 2013). "In CHepC, hepatic iron overload has been attributed to the mutation of the hemochromatosis protein (HFE) gene, since several reports have found an association between HFE genotypes and iron overload in patients with CHepC." (PMID 23653861, 2013). "The classic clinical presentation of HH with iron overload is associated with mutations in the HFE gene, namely, C282Y and/or H63D." (PMID 22157666, 2012). "The study of the C282Y and H63D mutations in the HFE gene in 9 patients with iron overload and hyposialia revealed 4 patients with a heterozygous genotype H63D and 3 cases with compound heterozygosity C282Y/H63D." (PMID 22157666, 2012). "A second missense mutation in the HFE gene, H63D, is found in about 4% of patients with HH, but its role in iron overload is still debated." (PMID 20196837, 2010). "The objective was to analyze the presence of C282Y, H63D and S65C mutations in the HFE gene and HLA-A alleles for a group of Brazilian patients with iron overload, and to correlate genotype with clinical and laboratory variables." (PMID 16878186, 2006). "The aims of the present study were to determine the prevalence of C282Y, H63D and S65C mutations in the HFE gene and HLA-A alleles in a selected group of Brazilian patients with iron overload, and to correlate genotypes with clinical and laboratory variables." (PMID 16878186, 2006). "However, the present study describes HFE mutation frequency, which is the main HH-related gene, in patients with iron overload treated at a public healthcare center specializing in hematology and hemotherapy in Santa Catarina." (PMID 40638437, 2025). "Initially, two theories were proposed to explain how an abnormal HFE protein causes iron overload." (PMID 40149659, 2025). "Iron overload may be seen in patients with mutations in the HFE gene, which is involved in iron metabolism." (PMID 40821324, 2025). "Iron overload has been reported in those who have digenic inheritance of one or more HFE mutations." (PMID 37686261, 2023). "In this regard, women with homozygous mutations in the HFE gene, which increase iron absorption, may be at risk of iron overload if they receive iron supplements." (PMID 36115950, 2022). "Interestingly, the studies demonstrated an association of HFE C282Y with iron deficiency anemia, in contrast with the expected role of this variant in iron overload." (PMID 36295058, 2022). "However, we focused on common genetic variants of the HFE gene, well described in relation to disorders associated with iron overload." (PMID 34291615, 2021). "Indeed, homozygosity for the C282Y HFE mutation is associated with the primary iron overload phenotype." (PMID 32429125, 2020). "The HFE gene is involved in the regulation of intestinal iron uptake, and variations in this gene, which are not very common, have been shown to increase the risk for hemochromatosis or iron overload." (PMID 30838211, 2019). "Mutations in the HFE gene reduce hepcidin expression in the liver, thus causing iron overload." (PMID 30271947, 2018). "As a second explanation, mutations in the HFE gene other than those tested in this study may be responsible for the iron overload and to higher serum ferritin." (PMID 27335591, 2016). "Expectedly, mutations in HFE cause the disruption of HFE function, leading to iron overload." (PMID 26893171, 2016). "This suggests that heterozygosis for the HFE mutation (responsible for mild iron overload) may trigger the clinical NAFLD manifestation." (PMID 27164079, 2016).
iron overload (continued). "Although it was not examined whether the patients were genetically predisposed to iron overload, the previously reported prevalence of the mutations of the HFE gene in Japanese population is less than 1%." (PMID 23653861, 2013). "Further, sequencing HFE introns and exons in English and French Canadian JH cases did not reveal novel HFE mutations that could likely explain the development of iron overload." (PMID 15610558, 2004). "Cançado and Chiattone showed that the frequency of the HFE gene in chromosome 6 with C282Y mutation among residents of São Paulo could explain this iron overload observed, which is three to eight times lower than the rate observed in whites from northern Europe." (PMID 34072813, 2021). "Several studies have demonstrated that mutation in the HFE gene and some other genes involved in iron homeostasis leads to down-regulation of hepcidin (Hepc) expression, and in consequence, promotes intestinal iron absorption, resulting in systemic iron overload." (PMID 34359361, 2021). "HFE mutation status may provide an important factor in early risk assessment, to be taken into account when tailoring transfusion protocols and chelation therapy to individual patients so as to minimize the risk of iron overload." (PMID 32414341, 2020). "Notably, several studies have found that certain variants of the HFE gene that increase risk of iron overload are more common in elite-level athletes compared to the general population, suggesting this may be beneficial for performance." (PMID 30838211, 2019). "So it is of interest to ask ourselves, for those patients with cirrhosis but without any known culprit as the cause, whether iron surcharge and mutations of the HFE gene that may induce this iron overload could play a relevant role in the etiopathogenesis of cryptogenic cirrhosis." (PMID 22509192, 2012). "HFE wt/wt women whose screening TS and SF were in the first and fourth quartiles of sex-specific distributions were not invited to post-screening evaluations, although their inclusion may have increased the prevalences of proven iron overload, iron overload-related disease, and iron deficiency." (PMID 41542669, 2026). "HH, an autosomal recessive disorder caused by the mutation of the homeostatic iron regulator (HFE) gene responsible for regulating iron homeostasis, is mainly manifested as a systemic iron overload." (PMID 36145059, 2022). "Multiple genetic variants have been shown to be associated with imbalanced iron-related biomarkers, resulting from iron overload or deficiency, particularly in genes involved in iron hemostasis pathways—TMPRSS6, HFE, TF, HAMP, TFR2 and SLC40A1." (PMID 36295058, 2022). "Variants at DUOX2, F5, SLC11A2 and TMPRSS6 associate with iron deficiency anemia, while variants at TF, HFE, TFR2 and TMPRSS6 associate with iron overload." (PMID 33536631, 2021). "Homozygozity for the c845G > A mutation within the HFE gene (OMIM: 613609) causing a substitution of the cysteine with a tyrosine residue in position 282 of the HFE gene product (p.Cys282Tyr) is, by far, the most frequent genetic form of iron overload." (PMID 30514216, 2018). "Consistently, NASH patients with a mutation in the HFE gene, which can lead to iron overload, have more severe hepatic fibrosis than those without this mutation." (PMID 37280194, 2023). "The HFE gene variant p.C282Y is unlikely to cause iron overload in the Asian β-thalassemia patients; the rarity of this variant in the study cohort replicates the findings of other South Asian population studies of this variant." (PMID 35903164, 2022). "The severity of iron overload increases in the order from HFE-/- to TFR2-/- to HJV-/- or HAMP-/-." (PMID 30608934, 2019). "Despite these high prevalence and association with the risk of iron overload the population of HFE H63D heterozygotes has not been widely examined, especially in children." (PMID 29362711, 2017).
iron overload (continued). "Several studies analyzed the role of HFE mutations in patients with NAFLD and iron overload." (PMID 27164079, 2016). "In the control group, 42.8% of the participants had this mutated genotype, which suggests that the presence of the mutations in the HFE gene is not a determining factor for the occurrence of iron overload." (PMID 26197432, 2015). "Additionally, the HFE mRNA level was elevated in ALD patients with iron overload compared with controls (1.40-fold, P = 0.0376)." (PMID 24894955, 2014). "Because this genetic test screens only for C282Y, H63D, and S65C mutations in the HFE gene, it is possible that our patient had a genetic predisposition to iron overload through non-HFE gene mutation mechanisms." (PMID 24024049, 2013). "The study therefore highlighted the presence of iron overload in many AML patients but did not support the evidence of an association between HFE mutations and iron overload in acute leukemia." (PMID 21687645, 2011). "Importantly, results were robust with or without inclusion of variants in the HFE gene, the commonest genetic cause of iron overload in the U.K." (PMID 36808173, 2023). "In patients with thalassemia intermedia, regardless of blood transfusion, the high risk of iron overload might be predicted by mutations in HFE gene." (PMID 31686454, 2019). "We found that the H63D mutation in the HFE gene was significantly more prevalent among women from Stratum 2 (initial Hb levels > 130 g/L) who developed iron overload, compared with women who completed the pregnancy without risk of hemoconcentration (41.4% and 19.8%, respectively, p = 0.045)." (PMID 31658725, 2019). "Therefore, we assessed iron metabolism and variants in the Homeostatic Iron Regulator gene (HFE) as the major cause of hereditary iron overload in a large cohort of Pi*ZZ subjects without liver comorbidities." (PMID 31717526, 2019). "The presence of the HFE protein at the interface between the brain and endothelial cells of the microvasculature, and in the cerebrospinal fluid (CSF), may also affect iron content and contribute to iron overload in neurodegenerative disorders." (PMID 30697143, 2018). "Although the presence of mutant C282Y allele in HFE protein is known to be associated with elevated serum markers of iron metabolism and iron tissue accumulation in CHC, HFE mutations cannot be considered a major factor leading to iron overload in HCV-infected subjects." (PMID 27125837, 2017). "The HFE protein was reported to be capable of forming a stable complex with transferrin receptor (TFR) to inhibit the abnormal up-regulation of the level of iron in cells, whereas the HFE C282Y mutation impairs the process and leads to peripheral iron overload." (PMID 27657935, 2016). "Iron overload in humans is associated with a variety of acquired and genetic conditions, the most common being the hereditary hemochromatosis type-I (HH, OMIM #235200), an autosomal recessive disorder caused by mutations in the HFE (High Iron Fe, OMIM *613609) gene." (PMID 26501199, 2015). "In this study, B2M knockout destabilized HFE on the adipocyte membrane, disrupting the HFE/B2M-TFR2-hepcidin-FPN axis and preventing HFD-induced iron overload." (PMID 41330906, 2025). "Abnormalities in the HFE gene, responsible for 90% of HH cases in individuals of Northern European descent, can lead to iron overload." (PMID 38333328, 2024). "Likewise, double Tfr2−/−Hfe−/− mice manifest more severe iron overload compared to single Tfr2−/− or Hfe−/− littermates, suggesting that TfR2 and HFE exhibit non-overlapping functions." (PMID 30420953, 2018). "In mice, blood lymphocyte numbers may influence iron overload severity in the absence of functional HFE protein." (PMID 16042809, 2005). "Based on our data from Hfe−/− mice, and the still limited number of clinical observations in HFE patients, we believe that osteoporosis does not primarily arise from iron overload." (PMID 31667458, 2019).
iron deficiency (18 papers, 2011 to 2026). "The HFE variant rs1800562 (also known as C282Y) exhibited a significant protective effect against iron deficiency in seven studies included in this review." (PMID 39599580, 2024). "It has been shown that heterozygosity or homozygosity for the C282Y variant of the HFE gene protects against the development of iron deficiency." (PMID 21483845, 2011). "Two HFE SNPs (rs1800562 and rs1799945) and one TF SNP (rs1799852) exhibited protective effects, while the other 11 SNPs were linked to increased risk of iron deficiency, suggesting potential benefits from iron supplementation for individuals with those genetic variants." (PMID 39599580, 2024). "Prevalence of iron deficiency in women by HFE p.C282Y and p.H63D allelesa." (PMID 32324809, 2020). "HFE overexpression in control mice results in increased hepatic hepcidin levels, p-Smad1/5 levels, and iron deficiency anemia, whereas overexpression of HFE in hepatocyte-specific Alk3-deficient mice results in no change in hepcidin, p-Smad1/5 levels, or blood parameters." (PMID 30271947, 2018). "In conclusion, the combination of high red meat consumption, low menstrual blood loss and the HFE C282Y mutation may protect from iron deficiency in women of childbearing age." (PMID 24663082, 2014). "Indeed, initiation of cART has been reported to increase sTFR levels, suggesting a state of functional iron deficiency in which cells with high metabolic demand for iron, such as neurons, may become iron-deficient; HFE variants could counteract these effects." (PMID 33057367, 2020). "Carriers of the minor allele of rs3811647 present a reduction in iron transport to tissues, which might indicate higher iron deficiency anaemia risk, although the simultaneous presence of the minor allele of rs1799852 and HFE mutations appear to have compensatory effects." (PMID 21978626, 2011). "HFE (rescaled by TSAT) and TMPRSS6 (iron) were strongly associated with inverse risk of iron-deficiency anaemia." (PMID 39643614, 2024). "Two studies analyzed TMPRSS6 and HFE variants in adult and pediatric celiac disease in which, as in IBD, iron deficiency anemia is a very common condition." (PMID 36295058, 2022). "In iron deficiency, the regulation pathway for iron status includes activity of the BMP/HJV and HFE/TFR2 complex." (PMID 24894955, 2014).
Cirrhosis (16 papers, 2016 to 2025). A chronic disorder of the liver in which liver tissue becomes scarred and is partially replaced by regenerative nodules and fibrotic tissue resulting in loss of liver function. "In HFE p.C282Y homozygotes, cirrhosis is positively associated with SF > 1000 μg/L at diagnosis and age at diagnosis, diabetes, amount of daily alcohol intake, and QFe." (PMID 35659379, 2022). "However, another study showed a different result revealing that a significant subgroup of homozygous for HFE C282Y had higher values of Ft and that this polymorphism is associated with cirrhosis." (PMID 41157574, 2025). "However, the HFE mutations didn’t seem to be associated with an elevated risk of HCC in cirrhosis patients." (PMID 34582652, 2021). "Cirrhosis develops in <10% of individuals homozygous for the C282Y variant in the homeostatic iron regulator (HFE) gene, where a gain-of-function variant of PCSK7 (rs236918) is associated with an increased risk of cirrhosis in this patient population." (PMID 35888711, 2022). "Other causes for cirrhosis were effectively ruled out with negative viral hepatitis, ceruloplasmin levels, and the HFE gene." (PMID 38559525, 2024). "We examined the association of all-cause cirrhosis with six genetic variants previously reported to be associated with alcoholic or non-alcoholic cirrhosis: PNPLA3 I48M, TM6SF2 E167K, MBOAT7 rs641738, HSD17B13 rs72613567, HFE C282Y and SERPINA1 E366K." (PMID 32282858, 2020). "We found strong correlations between genetic effects on HCC and hepatic steatosis (r2 = 0.75), and HCC and cirrhosis (r2 = 0.69), whereas only three loci (APOE, HFE, and TERT) had concordant effects on HCC and biliary tract cancer." (PMID 40823170, 2025). "The cirrhosis effects were proportional to the PDFF effects except for p.His48Arg in ADH1B (alcohol dehydrogenase 1b) and p.Cys282Tyr in HFE (homeostatic iron regulator)." (PMID 36280732, 2022). "The germline genetic testing was limited to the 226 cancer-predisposition genes included in the CZECANCA panel, which was designed for the analysis of cancer predisposition but does not cover some of the known cirrhosis-predisposing genes (i.e., APOB, HFE, PNPLA3, SERPINA1)." (PMID 36612198, 2022). "Our data demonstrated that HFE C282Y may increase the odds of developing HCC, while HFE H63D is more likely associated with susceptibility to HCC without cirrhosis in the African population." (PMID 27657935, 2016). "Moreover, HFE C282Y was significantly linked to the risk of HCC, while H63D was more likely to be involved in susceptibility to HCC without cirrhosis." (PMID 27657935, 2016).
diabetes (12 papers, 2010 to 2025). "In Northern-European ancestry populations, HFE gene C282Y mutations are relatively common (0.3%–0.6% rare homozygote prevalence) and associated with excessive iron absorption, fatigue, diabetes, arthritis, and liver disease, especially in men." (PMID 30657865, 2019). "In 769 postscreening HEIRS Study participants (including 188 p.C282Y homozygotes), log SF was significantly associated with diabetes in a regression model that included HFE genotype." (PMID 28331855, 2017). "In a large study of Danes reported in 2014, the mortality risk in individuals with diabetes was more than threefold greater in those with HFE p.C282Y/p.C282Y than in those with HFE wt/wt genotypes." (PMID 28331855, 2017). "By 12- weeks and 16-weeks post diabetes, the incidence of tortuous vessels, arteriovenous crossings and retinal vein occlusion with associated pigmentary abnormalities were much higher in diabetic HFE KO mice in comparison to diabetic HFE WT mice." (PMID 29445185, 2018). "The HFE p.C282Y+/+ (homozygous) genotype and central adiposity both increase liver disease and diabetes risks, but the combined effects are unclear." (PMID 39178373, 2025). "With an HFE knockout (KO) mice model of genetic iron overload, researchers found that iron overload during diabetes exacerbated DR progression." (PMID 36902565, 2023). "To understand if iron accumulation alters the pathogenesis of diabetic retinopathy, we induced diabetes in HFE KO mice, a genetic model of iron overload, using STZ." (PMID 29445185, 2018). "Further, we induced diabetes in HFE knockout (KO) mice model of genetic iron overload to understand the role of iron in the pathogenesis of DR." (PMID 29445185, 2018). "Given that H63D has less iron loading potential than the C282Y mutation, this raises the intriguing possibility of an iron‐independent role for the HFE protein in macronutrient metabolism that might protect against diabetes and NASH." (PMID 27354540, 2016).